FLNA (filamin A)
Diseases named in the same sentence as FLNA in open-access papers (continued):
Sharing a sentence is not in itself a finding about the gene and the disease.
prostate carcinoma (38 papers, 2011 to 2025). A carcinoma that arises from epithelial cells of the prostate gland. "Calcium has also been implicated in regulating filamin A cleavage, which is associated with migration in prostate cancer cells." (PMID 40151834, 2025). "As increased activity AR is heavily implicated in prostate cancer, the characterisation of filamin A's role in this disease has received much attention." (PMID 38958472, 2024). "Recently the role of the filamin A/AR signalling axis was uncovered in prostate cancer associated fibroblasts (pCAFs)." (PMID 38958472, 2024). "Based on TCGA data, FLOT1 expression is associated with FLNA expression in prostate cancer, consistent with the evidence above." (PMID 39404386, 2024). "Several studies reported the overexpression of Filamin A to be associated with highly metastatic cancers of the prostate, skin, and brain, and that Filamin A is involved in the progression of neoplasia." (PMID 36009568, 2022). "Among the concordant downregulated genes is FLNA, encoding filamin A, which is a regulator of the androgen receptor in prostate cancer." (PMID 34316327, 2021). "This study offers a potential new marker, the androgen receptor/filamin A complex, and a new therapeutic approach targeting intracellular pathways activated by the androgen/androgen receptor axis in prostate cancer-associated fibroblasts." (PMID 33500395, 2021). "The results indicate that calpains, most likely calpain 1, play a critical role in Cao2+-induced filamin A cleavage, which leads to a remodeling of actin cytoskeleton and an increase in the migration of AR-deficient prostate cancer cells." (PMID 27206800, 2017). "Filamin A can be cleaved to two fragments (~100 kD and 180 kD) in prostate cancer cells, and the cleavage of filamin A is associated with prostate cancer metastasis." (PMID 27206800, 2017). "Taken together, our results demonstrate that Cao2+ activates CaR-mediated signaling and induces the cleavage of filamin A via calpain activation, and this cleavage promotes the migration of AR-deficient and highly metastatic prostate cancer cells." (PMID 27206800, 2017). "Our further studies demonstrate that the cleavage of filamin A is regulated by CaR-mediated signaling and promotes the migration of AR-deficient prostate cancer cell lines." (PMID 27206800, 2017). "Meanwhile, filamin A is also found to be overexpressed in breast cancer and AR-deficient prostate cancer cells." (PMID 27206800, 2017). "Our data show that Cao2+ via CaR- mediated signaling induces filamin A cleavage and promotes the migration in AR-deficient and highly metastatic prostate cancer cells." (PMID 27206800, 2017). "Although we documented Cao2+- induced filamin A cleavage, and identified part of the CaR- mediated signaling pathway in AR-deficient and highly metastatic prostate cancer cells." (PMID 27206800, 2017). "Our results show that Cao2+ induces filamin A cleavage and promotes migration in AR-deficient and highly metastatic prostate cancer cells via a CaR-p115RhoGEF-calpain signaling pathway." (PMID 27206800, 2017). "Accumulating evidence indicates that FLNA dysregulation is implicated in various cancer types, including breast cancer, parathyroid carcinoma, adrenocortical carcinoma, and prostate cancer." (PMID 41367384, 2025). "As such, this review synthesizes existing literature on several ABPs linked to prostate cancer, including cofilin, filamin A, and fascin, with the aim of shedding light on the molecular mechanisms through which ABPs influence prostate cancer development and identifying potential therapeutic targets." (PMID 39055653, 2024). "Whether CaR-mediated signaling is involved in filamin A cleavage and regulating migration in AR-deficient and highly metastatic prostate cancer cells is still unknown." (PMID 27206800, 2017).
prostate carcinoma (continued). "Furthermore, Cao2+-induced filamin A cleavage is a CaR- p115RhoGEF-calpain dependent process, and the cleavage of filamin A promotes the migration of AR- deficient and highly metastatic prostate cancer cells." (PMID 27206800, 2017). "In this study, we compared the expression and cleavage of filamin A in normal prostate and prostate cancer cells, explored how Cao2+ regulates the cleavage of filamin A in prostate cancer cells, and determined whether the cleavage of filamin A is associated with prostate cancer cell migration." (PMID 27206800, 2017). "The recent observation that high levels of cytoplasmic FlnA are a hallmark of metastatic prostate cancer supports the hypothesis that AR/FlnA complex detected upon androgen stimulation in cytoplasm of embryonic fibroblasts might be recapitulated during cancer progression and invasiveness." (PMID 21359179, 2011). "Further to its role in prostate cancer in directly binding the AR and maintenance of membrane localised PMSA filamin A cleavage by calpain represses tumour metastasis in AR-positive prostate cancer, and its subcellular localisation is key to this." (PMID 38958472, 2024). "In the case of AR positive prostate cancer cytoplasmic filamin A is cleaved and the 90 kDa fragment translocates to the nucleus, where it inhibits AR activity, resulting in decreased metastatic potential." (PMID 38958472, 2024). "Contradictory to its role in AR-positive prostate cancer, filamin A cleavage by calpain augments tumour cell metastasis in a calcium-dependent manner." (PMID 38958472, 2024). "Decreased nuclear and elevated cytoplasmic localisation of filamin A is apparent in the androgen-refractory (hormone-resistant) prostate cancer cells." (PMID 38958472, 2024). "Evidenced by immunohistochemical and in vitro studies, prostate cancer cell invasion is promoted by cytoplasmic localisation of filamin A and suppressed by filamin nuclear localisation." (PMID 38958472, 2024). "Such potential therapeutics include Genistein combined polysaccharide, which is a natural product, promotes filamin A nuclear localisation by cleavage, and is a recognised as a potential treatment of prostate cancer." (PMID 38958472, 2024). "Overall, these findings show that the androgen stimulates cell motility of LNCaP prostate cancer cells forming a complex with Filamin A, which, in turn, stimulates Rac and Fak activation." (PMID 35011576, 2021). "In turn, in prostate cancer, nuclear FlnA interacts with androgen receptor and inhibits the transcription of its target gene." (PMID 33036298, 2020). "Through the application of bioinformatics technology, we identified the potential key genes associated with the occurrence and development of prostate cancer as FGF2, FLNA, VCL, FLNC, CAV1, ACTC1, and MYLK." (PMID 32547947, 2020). "In prostate cancer, the cytoplasmic localization of FLNA determines a propensity to metastasize that can be prevented by cleavage and subsequent nuclear translocation." (PMID 31632499, 2019). "This study aims to investigate the association of filamin A with the function and morphology of prostate cancer (PCa) cells, and explore the role of filamin A in the development of PCa, in order to analyze its significance in the evolvement of PCa." (PMID 31268639, 2019). "Immunoblotting results indicated that calpeptin (40 μM for 24 h) effectively inhibited calpain activity, and protected filamin A and androgen receptor from cleavage by calpain in human prostate cancer cell lines PC-3." (PMID 30448882, 2019). "Benjamin A Mooso et al20 found that, induction of the nuclear localization of filamin A, promoted apoptosis in prostate cancer cells and inhibited the proliferation of transplanted tumors in vitro." (PMID 29862660, 2018).
prostate carcinoma (continued). "Selected ARA-lincRNAs are neighbors of protein-coding genes WDR5, ZNF706, TFRC, and FLNA, which have been described as up-regulated in prostate cancer, and of CENPH and RAB11FIP3, which have been shown to play a role in many other types of cancer." (PMID 29875794, 2018). "Increasing nuclear filamin A fragment induces prostate cancer cell apoptosis during androgen deprivation therapy (ADT)." (PMID 27206800, 2017). "This study reports on the development of a novel serum protein panel of three prostate cancer biomarkers, Filamin A, Filamin B and Keratin-19 (FLNA, FLNB and KRT19) using multivariate models for disease screening and prognosis." (PMID 29682400, 2017). "Akt-dependent phosphorylation of filamin A at S2152 has been previously determined in prostate cancer cells and the IGF-1-treated MCF-7 cells." (PMID 25944616, 2015). "Filamin A localisation depends on the type and progression of prostate cancer." (PMID 38958472, 2024). "In prostate cancer therapy, long-term androgen deprivation leads to increased FLNA expression; however, once FLNA is localized to the nucleus, it can enhance the responsiveness of castration-resistant prostate cancer cells to androgen deprivation therapy by inducing apoptosis." (PMID 38584831, 2024). "Moreover, AR is found in a complex with FLNA, and the AR/FLNA complex was suggested to be a target in the prostate cancer microenvironment, for example, by using an AR-derived stapled peptide, which disrupts the AR/FLNA complex assembly." (PMID 38255186, 2023). "In the current study, we evaluated the clinical utility of a multiple variable prostate cancer biomarker panel test on the analysis of 777 patients assessed the combinatorial power of filamin-A (FLNA), age, and prostate volume in predicting separation of BPH versus PCa diagnoses compared to PSA." (PMID 34302010, 2021). "Among the many functions, FLNA interacts with AR reducing its activation in prostate cancer." (PMID 32626651, 2020). "Low nuclear FlnA levels are characteristic for colorectal adenocarcinoma and prostate cancer." (PMID 33036298, 2020). "The Filamin A gene has been shown to be involved in the development and progression of PCa, and further studies of the biological function of Filamin A may provide a new perspective for the overall treatment of prostate cancer." (PMID 31268639, 2019). "Furthermore, elevated levels of filamin A in circulating plasma has been reported to be a specific and sensitive marker for patients with metastatic breast and prostate cancer." (PMID 29596499, 2018). "In the present study, we further demonstrate that GPCR signaling, independent of AR, can activate the cleavage of filamin A to promote cell migration in AR- deficient and highly metastatic prostate cancer cells." (PMID 27206800, 2017). "Overexpression and enhanced activity of calpain-2 also induces an increase in the fragmental cleavage of AR and FlnA, which may contribute to the development of an aggressive phenotype of prostate cancer." (PMID 27689993, 2016). "The overexpression of calpain 2 and increased expression of FlnA may contribute to the development of an aggressive phenotype of prostate cancer." (PMID 24297527, 2014). "The contrasting distribution of FlnA in the nucleus or in the cytoplasm is consistent with clinical data in which immunohistochemistry analysis demonstrated that cytoplasmic localization of FlnA is highly correlated with metastases of prostate cancer." (PMID 24297527, 2014). "Further, cytoplasmic localization of FlnA has been correlated with metastatic and hormone-refractory phenotypes in human prostate cancer, suggesting that intracellular localization of FlnA orchestrates invasiveness and even hormone responsiveness of prostate cancers." (PMID 21359179, 2011). "FlnA and its proteolytic fragments directly interact with AR, thereby modulating nuclear translocation and transcriptional action of AR as well as androgen dependence of prostate cancer LNCaP cells." (PMID 21359179, 2011).
prostate carcinoma (continued). "In prostate cancer filamin A is speculated to possess tumour-supressing properties." (PMID 38958472, 2024). "It is unknown if filamin A in plasma of breast or prostate cancer patients is carbonylated." (PMID 29596499, 2018). "However, the signaling pathway that regulates filamin A cleavage and cell migration in AR- deficient prostate cancer cells has not been studied." (PMID 27206800, 2017). "Among these genes, high expression of certain genes, such as FLNA and DSTN, is positively correlated with the prognosis of prostate cancer patients, while elevated expression of other genes, including FLNB and INF2, is associated with a negative prognosis." (PMID 41049007, 2025). "A recent study by this group discovered three novel biomarkers, FLNA, FLNB and KRT19 for prostate cancer." (PMID 29682400, 2017). "Lastly, the stapledpeptide used in this study, as well as other small molecules capable ofdisrupting the AR/FlnA interaction, might represent a promising approach tospecifically modulate AR functions in stromal tissue and rescue hormoneproliferative responsiveness in human prostate cancers." (PMID 25476896, 2014). "The prostate cancer metastasis correlates with cytoplasmic localization of full-length filamin-A but not nuclear filamin-A fragments." (PMID 23388158, 2013). "Disruption of the AR/filamin A complex using a stapled peptide effectively reduces CAF invasiveness and tumor growth in co-culture models, suggesting the potential for targeting this complex as a therapeutic strategy to enhance treatment outcomes in prostate cancer." (PMID 40008000, 2025). "Majority of the prostate cancers (75%), however, showed no Filamin A expression." (PMID 30623593, 2019). "To investigate whether filamin A plays an important role in prostate cancer metastasis, we first assessed the expression of filamin A in human nonmalignant prostate epithelial cells (PE), LNCaP, DU145 and PC-3 cells." (PMID 27206800, 2017). "Interestingly, the accumulation of CRL substrates induced by SAG knockdown was rather selective, since other two SCF/CRL1 substrates p21 and p27, two CRL5 substrates FLNA and DAB1, and one CRL3 substrate NRF2 were not accumulated in these two lines of prostate cancer cells upon SAG depletion." (PMID 27955654, 2016).
breast cancer (36 papers, 2011 to 2025). A primary or metastatic malignant neoplasm involving the breast. "All of these, with the exception of TCP1, have also been linked to breast cancer, while FLNA, GSK3B and CCT2 are specifically linked to TNBC." (PMID 32127582, 2020). "Next, the associations between FLNa protein expression and the clinicopathological features of the patients with breast cancer were investigated." (PMID 24137390, 2013). "In addition, FLNA, whose overexpression is associated with the advanced stage, lymph node metastasis, and vascular or neural invasion of breast cancer." (PMID 30906311, 2019). "The present ex vivo data supported the hypothesis that FLNa expression is associated with breast cancer development and progression." (PMID 24137390, 2013). "Overexpression of the FLNa protein was associated with advanced stage, lymph node metastasis, vascular or neural invasion, menstruation state and other risk stratifications for breast cancer." (PMID 24137390, 2013). "FLNa mRNA and protein were overexpressed in breast cancer tissues, which was associated with advanced stage, lymph node metastasis and vascular or neural invasion of breast cancer, suggesting that FLNa contributes to breast cancer development and progression." (PMID 24137390, 2013). "The overexpression of FLNa has been associated with the invasion and metastasis of breast cancer." (PMID 24137390, 2013). "The X‐linked cancer‐related genes FLNA, PFC, PRPS1, TARD8, MAGEE1, TAF, and KLH4 have all been associated with breast cancer." (PMID 38827026, 2024). "A number of X‐linked cancer‐related genes, including FLNA, PFC, PRPS1, TARD8, MAGEE1, TAF, and KLH4 have been associated with breast cancer." (PMID 38827026, 2024). "In the MCF-7 breast cancer cell, Akt was identified to phosphorylate filamin A at S2152 following insulin-like growth factor I stimulation, an effect abolished by inhibition with PI3K inhibitor wortmannin." (PMID 38958472, 2024). "Most researchers concluded that overexpression of FLNa contributes to increased motility and invasive properties of breast cancer cells." (PMID 38666944, 2024). "On the other hand, FLNa has also been found to regulate focal adhesion disassembly and inhibit breast cancer cell migration and invasion." (PMID 38666944, 2024). "On the other hand, breast cancer cells’ motility was increased by upregulating phosphorylated PAK1 through FLNa." (PMID 38666944, 2024). "There is evidence to suggest that in the case of breast cancer, cyclin D1 interacts with FLNa, which promotes the migration and invasive potential of cancer cells." (PMID 38666944, 2024). "The significant correlation between FLNa overexpression and breast cancer has led to extensive research into its potential as a diagnostic marker for the disease." (PMID 38666944, 2024). "To evaluate FLNa’s potential as a therapeutic target, we have summarized its roles in breast cancer." (PMID 38666944, 2024). "FLNa’s role has been identified in a wide range of cancer types, including prostate, pancreatic, lung, colorectal, gastric, and breast cancers when compared to healthy tissues." (PMID 38666944, 2024). "Remarkably, their study highlighted a panel of four proteins, including FLNa, which demonstrated a capability to distinguish breast cancer patients with 100% sensitivity and 85% specificity at early T1a stages." (PMID 38666944, 2024). "All shreds of evidence strongly support that FLNA is a positive driver gene of breast cancer metastasis." (PMID 35359350, 2022). "Of them, filamin A (FLNA) showed the most potential in regulating breast cancer metastasis and PFS, in particular in TNBCs." (PMID 35359350, 2022). "Taken together, miR-200c expression showed an indirect proportional relation to filamin A protein as well as mRNA in two complementary breast cancer cell line models." (PMID 31747409, 2019). "We also found strong indications of a regulatory network of miR-200c and FLNA in both breast carcinoma models." (PMID 31747409, 2019).